BRAF (B-Raf proto-oncogene, serine/threonine kinase)
Diseases named in the same sentence as BRAF in open-access papers (continued):
Sharing a sentence is not in itself a finding about the gene and the disease.
melanoma (continued). "Depleting MDSCs by using antibodies (anti-Gr-1) or blocking their recruitment (CCR2 antagonist) did not allow the growth of BRAF-resistant melanoma tumors." (PMID 35328639, 2022). "Belvarafenib is a type II RAF inhibitor and is effective in BRAF V600E‐ and NRAS‐mutant melanoma." (PMID 36254250, 2022). "In vitro, combined BRAF and MEK inhibition can induce rapid, non-mutational drug resistance, with a subpopulation of BRAF V600 mutant melanoma cells undergoing a reversible remodelling of mRNA translation." (PMID 35538491, 2022). "The ERK pathway has been reported to activate Rac activity in BRAF- and NRAS-mutant melanoma." (PMID 35625714, 2022). "EGCG (5 μM) inhibits melanoma cell growth independent of BRAF inhibitor sensitivity by regulating the activity of PP2A." (PMID 36014370, 2022). "Combining BRAF and MEK inhibition is a new strategy for the management of melanoma." (PMID 35742834, 2022). "Additionally, it has been proposed that BRAF inhibitors support and enhance the anti-proliferative IFN-alpha effect on melanoma cells." (PMID 35163468, 2022). "They showed that PDGFRb could be transferred via EVs from resistant melanoma cells to recipient melanoma cells, resulting in a dose-dependent activation of PI3K/AKT signaling and escape, thus resistance, from BRAF inhibition." (PMID 36289847, 2022). "In the high-fat keto diet-fed mice, atorvastatin treatment induced minimal inhibition of tumor growth in BRAF inhibitor-acquired-resistant (A375R1) and intrinsic BRAF inhibitor-resistant (UCSD354L) melanoma cell lines compared with the vehicle, as was also observed in mice fed with a regular diet." (PMID 36143915, 2022). "Previously, ‘driver-negative’ (i.e. the absence of BRAF, NRAS, KIT, GNAQ or GNA11 mutations) melanoma cell-lines that were less sensitive to trametinib and which displayed paradoxical activation of MEK1/2, were found to show basal EGFR activation due to AREG." (PMID 35993275, 2022). "Importantly, there is also some evidence that in melanoma cells, the nuclear accumulation of the two transcriptional co-activator paralogs and mechanotransducers YAP and TAZ promotes resistance to BRAF inhibitors." (PMID 36119516, 2022). "Compared with BRAF, we suggest that MUC16 may be a more suitable biomarker for detecting the transformation of GCMN to melanoma in the Chinese population." (PMID 36085074, 2022). "Notably, high expression of EGFR results in a slow-growth phenotype with melanoma cells, but EGFR turned into a cancer-promoting factor and contributed to the targeted therapy resistance to BRAF or MEK inhibitors." (PMID 35692844, 2022). "BRAF class II mutations have constitutively activated BRAF dimers independent of RAS activation, and BRAFG469V has been shown to confer sensitivity to trametinib in melanoma and lung cancer." (PMID 34737188, 2022). "In particular, it could be interesting to study UBIAD1/CoQ10/NQO1 axis in those situations where oxidative stress drives resistance to therapy (e.g. BRAF and MEK inhibitors-resistant melanoma)." (PMID 35255427, 2022). "In addition, since BRAF suppresses mitochondrial function via the downregulation of MITF, melanoma cells treated by BRAF-targeted drugs restore oxidative phosphorylation to maintain their survival, leading to adaptive resistance to targeted therapy." (PMID 36003368, 2022). "Since EGFR mediates resistance to BRAF inhibitors, the differing expression of EGFR in CRC, compared to melanoma, may explain this difference in response rates." (PMID 36530921, 2022). "Whole exome sequencing of drug resistant tumors revealed the recurrent copy number gain of BRAF V600E at a frequency of 19%-28% as a common resistant mechanism to RAFi in melanoma, which hyperactivates ERK signaling independent of CRAF 80, 83-85." (PMID 35966590, 2022). "Given the presence of the two oncological pathologies, a biopsy of the dorso-lumbar spine was performed, which established that the bone lesions were metastases of melanoma, BRAF negative." (PMID 35911362, 2022).
melanoma (continued). "RAS-GTP levels increased in NRAS- or BRAF-mutant melanoma cells without a change in total RAS protein." (PMID 35197475, 2022). "The BRAF is a gene that consists of RAS in terms of the MAP kinase signalling route, and it produces MEK to phosphorylate ERK, which enriches cell growth in melanoma." (PMID 36551688, 2022). "We base our model on data obtained in MEL06 patient-derived melanoma cells, which were demonstrated to develop non-genetic resistance to BRAF/MEK inhibitors." (PMID 35494017, 2022). "The majority of the 1505 patients across CheckMate 066, 067, and 069 had melanoma stage IV, M1c, BRAF wild-type disease, and no history of brain metastases." (PMID 35565428, 2022). "A study of adjuvant combination therapy with BRAF inhibitor, dabrafenib, and MEK inhibitor, trametinib, in patients with resected stage III BRAF V600E/K-mutant melanoma showed improved recurrence free survival benefit at 3 years with overall survival rate of 86% compared to 77% with placebo." (PMID 36212431, 2022). "An open-label phase I trial examined the intratumoral injection of a non-neurovirulent rhinovirus:poliovirus chimera (PVSRIPO) in patients with refractory melanoma stage IIIB-IV that showed disease progression on anti-PD-1 and BRAF/MEK inhibitors, if BRAF mutant." (PMID 35740539, 2022). "Since both BRAF/MAPK and PI3K/Akt signaling axes impinge on mTORC1 activity in the presence of sufficient amino acid levels, mTORC1 activation in response to BRAF or MEK inhibition has been monitored in BRAFi sensitive and BRAFi resistant BRAFV600E melanoma cells." (PMID 36077374, 2022). "Although the combined use of BRAF and MEK inhibitors has shown a better effect in the clinical treatment of melanoma patients, some clinical adverse reactions are quite common in combination schemes, such as vomiting, nausea, fatigue, headache, arthralgia and so on." (PMID 36551302, 2022). "It is a tamoxifen-inducible mouse model that activates malignant transformation of melanocytes by oncogenic activation of BRAF (BRAFV600E mutation) in the absence of PTEN, a combination that mimics a major process during clinical melanoma progression." (PMID 35422482, 2022). "Both ICIs and BRAF and MEK inhibitors can be effective in patients with BRAFV600E mutant melanoma." (PMID 36016960, 2022). "However, a recent study reported that although BRAF increases ERK3 transcription and stability, ERK3 expression in melanoma cells suppresses cell growth." (PMID 35022544, 2022). "BRAFi efficacy has been reported in basket trials across diverse nonmelanoma BRAF-mutant cancers, although overall response rates are generally lower than as observed in melanoma." (PMID 35486732, 2022). "The last few years has seen a significant advance in our understanding of the role ERK5 in certain malignancies, most notably in melanoma where components of the entire core pathway are amplified or upregulated and where ERK5 activation can drive resistance to BRAF, MEK or ERK1/2 inhibitors." (PMID 35903549, 2022). "Furthermore, it has been suggested that the activation of BRAF, NRAS, and PI3K can occur in various stages of melanoma development." (PMID 36614156, 2022). "Despite remarkable progress in our understanding of tumor immunity and genomic analysis in recent decades, which has led to the development of novel immune checkpoint inhibitor and BRAF/MEK inhibitor therapies for melanoma, the treatment of patients with advanced melanoma remains challenging." (PMID 35163233, 2022). "AQP1 was found to be overexpressed in BRAF-mutant melanoma tumors and was shown to be a negative prognostic factor." (PMID 35269844, 2022).
melanoma (continued). "Treatments with BRAF and MEK inhibitors have been shown to increase ROS in melanoma." (PMID 35326089, 2022). "Furthermore, it is described that silybin is an inhibitor of the BRAF-MEK-ERK-RSK2 pathway, which is an important pathway for the growth, proliferation, and survival of melanoma." (PMID 35877341, 2022). "Interestingly, it is shown that heterozygous (but not homozygous) Atg5 loss compromised the response of BRAF inhibitors in melanoma-specific mouse models, raising caution about the incomplete blockade of this gene in clinical aspects, since this may cause an unexpected worsening of patient outcomes." (PMID 35563798, 2022). "We found that patulin and LL‐Z1640‐2 reduced ZIC5 protein levels and induced apoptosis in many tumour cell lines, including BRAF inhibitor‐resistant melanoma cells, but not in NHMs." (PMID 36282887, 2022). "The braftovi/mektovi (BRAF/MEK) inhibitor-induced pyroptosis can induce changes in the tumor immune microenvironment and improve the therapeutic effect of drug-resistant melanoma, which provides a new direction for scorch-mediated anti-tumor immunity and treatment of drug-resistant tumors." (PMID 35883480, 2022). "Of note, while glutamine dependence underlies the resistance to the BRAF inhibitor, local deprivation of glutamine in melanoma TME increases histone hyper-methylation, which contributes to tumor cell dedifferentiation and also results in resistance to BRAF inhibitor treatment." (PMID 36003368, 2022). "This led to the combination of BRAF and MEK inhibitors in clinical trials, which showed a significant improvement in overall survival compared with single-agent therapy, and subsequently FDA-approved treatment for advanced BRAFV600E-positive melanoma." (PMID 34737188, 2022). "BRAF and MEK inhibitors, while useful for treating BRAF-mutant melanoma, have no or limited effectiveness against RAS mutants." (PMID 35560144, 2022). "In contrast, and as we report in the current study, WT BRAF does not show any nuclear localization by immunofluorescence in the SKMel-202 melanoma cell line." (PMID 35053476, 2022). "Another strategy that allows melanoma cells to bypass BRAF inhibitors (BRAFi) treatment is not genetic, but implies phenotype switching." (PMID 35956175, 2022). "Currently, there are three BRAF (vemurafenib, dabrafenib, encorafenib) and three MEK inhibitors (trametinib, kobimetinib, binimetinib), as well as their combinations approved for advanced melanoma treatment." (PMID 35565444, 2022). "For example, melanoma patients acquire resistance to RAF inhibitors through generating spliced isoforms of BRAF V600E in the absence of RAS-binding domain." (PMID 36505780, 2022). "The only biomarker to date that looks useful is BRAF mutation status, with the combination having a PFS and OS benefit over nivolumab monotherapy in patients with BRAF-mutant melanoma but not BRAF wild-type." (PMID 35449104, 2022). "In fact, a recent whole-genome sequencing analysis conducted in yeast repeatedly exposed to UV identified novel UV mutation signatures induced by the formation of atypical, but highly mutagenic, photoproducts that were present in human skin cancers such as BRAF- and NRAS-mutant melanomas." (PMID 35804995, 2022). "Melanoma MV3 cells, which express WT BRAF, were transduced with the three different viral vectors." (PMID 35053476, 2022). "A study showed that treatment of melanoma cells with BRAFi induces STAT3-dependent expression of SOX2, which, together with CD24, contributes to create an autoregulatory loop that sustains adaptive resistance to BRAF-targeted therapy." (PMID 35944584, 2022). "However, despite an initial robust response to BRAF- and MEK-targeted therapies, patients with melanoma typically acquire treatment resistance within a few months, resulting in disease progression." (PMID 35785205, 2022).
melanoma (continued). "Importantly, under hypoxic conditions, AZD7762 kills cells both sensitive and resistant to BRAF inhibition and induces a significant tumor growth delay in vivo in PDX melanoma cells with primary resistance to vemurafenib (PLX4032)." (PMID 35563772, 2022). "As expected, BRAF inhibition induced a rapid tumor reduction, whereas imatinib alone did not display a significant anti‐melanoma effect." (PMID 34957688, 2022). "The systemic treatment landscape for advanced (i.e. unresectable stage IIIc or IV) melanoma patients has dramatically changed in recent years with the introduction of immunotherapies (CTLA-4 and PD-1 inhibitors) and targeted therapies (BRAF- and MEK-inhibitors)." (PMID 35703270, 2022). "Cells lacking USP7 show an increased susceptibility to BRAF inhibitors, which makes this DUB a good therapeutic target in melanoma in combination with existing treatments." (PMID 35884430, 2022). "We also found that patients with melanoma who did not respond to BRAF-targeted therapy had plasma lipid profiles that were different from patients who responded to this therapy." (PMID 35565240, 2022). "Together, these results suggest BRAF and RAF1 fusions are drivers of MAPK signaling in melanoma." (PMID 35326655, 2022). "Immunohistochemical (IHC) analysis of BRAF V600E melanoma patient-derived biopsies highlighted that patients with abundant stromal HGF showed a poorer response to BRAF inhibitors than those lacking stromal HGF." (PMID 36324182, 2022). "Treatment of melanoma cells with BRAFV600E/K or pan-RAF inhibitors (PLX4032 or LY3009120) reduced shLZTR1-induced pERK activation, rendering further support for the role of BRAF kinase activity." (PMID 35197475, 2022). "Changes in these genes are identified in samples of melanomas of patients with a worse response to targeted therapy (time to progression (TTP) < 4 months; and in patients with primary and acquired resistance to BRAF inhibitors." (PMID 35565444, 2022). "Given the prevalence of BRAF and PTEN alterations in human melanoma, our results, which demonstrated that in vivo targeting of Loxl3 was deleterious to melanomagenesis in a mouse model harboring activated BrafV600E and loss of Pten, warrant future strategies aimed at blocking cellular LOXL3." (PMID 35267510, 2022). "The combination of BRAF and MEK inhibitors was shown to induce pyroptosis in melanoma cells via GSDME which resulted in an increase in CD4+ T cell and CD8+ T cell infiltration and a decrease in myeloid-derived suppressor cells (MDSCs) and tumor-associated macrophages (TAMs)." (PMID 36605187, 2022). "In all melanoma models examined, and irrespective of their BRAF status, INHBA expression reduced the frequency of intratumoral CTLs and NK cells." (PMID 35580932, 2022). "Consequently, at present, B-Raf and MEK inhibitor combined treatment is the preferable choice for patients with BRAF V600-mutant melanoma." (PMID 36143375, 2022). "Thus, our findings support that BRAF mutations alone do not predict the risk of metastasis development or melanoma survival and that miR-125b, miR-200c and miR-205 may be considered as accurate prognostic biomarkers in melanoma regardless of BRAF mutational status." (PMID 35326682, 2022). "We applied this to zebrafish with BRAF-mutant melanoma, a model that has significantly advanced our understanding of melanoma progression, but not of drug resistance due to the limitations of current treatment methods." (PMID 35394030, 2022). "The use of inhibitors such as those targeting BRAF (vemurafenib, dabrafenib) and MEK (trametinib, selumetinib, cobimetinib) in BRAFV600E-positive melanoma resulted in a moderate success of targeted therapies by showing tumor shrinkage and improving patient survival." (PMID 34737188, 2022). "Indeed, it is upregulated by the oncogenic kinases BRAF and NRAS, and its overexpression in melanoma cells promotes proliferation and leads to tumor formation when overexpressing cells are injected in mice." (PMID 36286041, 2022).
melanoma (continued). "BRAF and MEK inhibitors improve clinical outcomes, and anti-PD1 therapy demonstrates better results than chemotherapy or anti-CTLA4 therapy in terms of the survival of patients with advanced melanoma." (PMID 36844955, 2022). "Similarly, the lack of DNMT3B significantly inhibits melanoma formation in the BRAF/phosphatase and tensin homolog (PTEN) mouse melanoma model." (PMID 36091786, 2022). "Future studies in evaluating optimal treatment sequencing in rare, non-classical BRAF-mutant melanoma patients would be important, especially to identify if TT is less effective in rare BRAF mutations compared to classical BRAF V600E/K mutations." (PMID 35323326, 2022). "UACC903 cells, a different human BRAF mutant melanoma cell line, showed a similar lack of beta-galactosidase staining and SASP induction in AKT1 cells, with a modest effect in AKT3 knockout cells as well, showing this phenotype is not cell-line specific." (PMID 35158840, 2022). "In BRAF mutant melanomas, GPNMB is upregulated after BRAF/MEK inhibitor therapy." (PMID 35158847, 2022). "Consequently, we established BRAFi-R melanoma cell lines by gradually exposing BRAFi-sensitive HTB63 and A375 cells to increasing concentrations of two different BRAF inhibitors (PLX4032 or PLX4720)." (PMID 36551563, 2022). "As a result, HRAS mutant squamous- and head and neck cancers, NRAS mutant novel melanomas or myelomonocytic leukemia and KRAS mutant colorectal cancers could be developed upon BRAF inhibitor therapies." (PMID 36213163, 2022). "Combined BRAF, MEK, and CDK 4/6 inhibition showed promising anti-tumor activity, driven by reducing the population of tumor-intrinsic myeloid cells in syngeneic mouse models of melanomas." (PMID 36145516, 2022). "However, this study was conducted in 2012, when checkpoint inhibitors or BRAF/MEK inhibitors were unavailable, and systemic therapy is currently the standard treatment for distant metastases of melanoma." (PMID 35954498, 2022). "Furthermore, combinations of BRAF inhibitors and MEK inhibitors in BRAF mutant melanoma promoted cleavage of GSDME and regulated the tumor immune microenvironment via pyroptosis." (PMID 35646948, 2022). "Moreover, combined treatment with BRAF and MEK inhibitors induces GSDME-dependent pyroptosis in melanoma cells and subsequently increases the number of intratumoral CD8+ T cells." (PMID 35990696, 2022). "Furthermore, we demonstrate that the HSPB8-mediated autophagy activation is a crucial event to prevent proliferation and migration of both BRAF- and NRAS-mutant melanoma." (PMID 36400750, 2022). "Altogether, these data confirmed the contribution of PFKFB2/PFKFB3 to the survival response to metabolic stress in NRASQ61 mutant melanomas, revealing a link between the RAS and glycolytic pathways, which implies the regulation of PFKFB2 by BRAF and probably ERK proteins." (PMID 36402789, 2022). "Vemurafenib, an inhibitor of mutant BRAF used for the treatment of melanoma, also inhibits PTK6, but not SRC, at nanomolar concentrations." (PMID 36228719, 2022). "Specifically, we could resolve the coordinated and synchronized assembly (and disassembly) of NRas and BRAF in co-clusters at the PM of live, EGF-activated 108T melanoma cells." (PMID 36304112, 2022). "In addition, YAP was also observed to play an important role in regulating the sensitivity of BRAF and KRAS mutant cancer cells to specific drugs, and the invasive activity of melanoma in vitro and in vivo." (PMID 35141161, 2022). "Furthermore, a higher expression of adipocyte enhancer-binding protein 1 (AEBP1) has been shown to confer resistance to BRAF inhibition in vivo, and greater CREB activation is required for AEBP1 overexpression in resistant melanoma cells." (PMID 35805104, 2022). "Currently, combined BRAF/MEK and immunological checkpoint inhibition, which are encountered even in adjuvant and neoadjuvant contexts, are flagships for unresectable melanomas." (PMID 36555289, 2022).